RN7SL691P (RNA, 7SL, cytoplasmic 691, pseudogene)
Gene: Miscellaneous RNA gene on chromosome 4 (43,598,544 to 43,598,844, reverse strand). Ensembl gene ENSG00000239464.
Homologues: Orthologues: chimpanzee Metazoa_SRP (99% identical), macaque Metazoa_SRP (88% identical), dog Metazoa_SRP (57% identical). Paralogues in human: RN7SL1 (82% identical), RN7SL2 (81% identical), RN7SL3 (81% identical), RN7SL230P (78% identical), RN7SL823P (78% identical), RN7SL679P (78% identical), RN7SL145P (77% identical), RN7SL45P (77% identical), RN7SL655P (77% identical), RN7SL709P (77% identical), RN7SL296P (77% identical), RN7SL664P (77% identical), and 702 more.